TNF (tumor necrosis factor)
Diseases named in the same sentence as TNF in open-access papers (continued):
Sharing a sentence is not in itself a finding about the gene and the disease.
psoriasis (continued). "It has been reported that fatty acids like linolenic acid, palmitic acid, and oleic acid extracted from the seeds of the herb are used to treat atopic dermatitis and psoriasis by impeding the NF-kB pathway, and cytokines like IL-6, TNF-α, etc." (PMID 40154100, 2025). "Current research focuses on the phytochemical and pharmacoinformatics analysis of VT oil preparation to elucidate its potential against key inflammatory proteins (TNF-α, IL-17A) involved in psoriasis." (PMID 40892753, 2025). "An in vitro model of psoriasis was established by stimulating keratinocyte HaCaT with a mixture of five pro-inflammatory cytokines (IL-17 A, IL-22, IL-1α, oncostatin M, and TNF-α) (M5)." (PMID 40197419, 2025). "Multiple inflammatory mediators and signaling pathways contribute to the pathophysiology of psoriasis, including tumor necrosis factor (TNF), prostaglandin–endoperoxide synthase 2 (PTGS2), and interleukin-17A (IL-17A)." (PMID 41471291, 2025). "Psoriasis is accompanied by increased concentrations of inflammation- and angiogenesis-related mediators such as TNF-α, IL-17, and VEGF." (PMID 41465162, 2025). "Adipose tissue is a source of various proinflammatory cytokines, including adiponectin, leptin, resistin, TNF-α, and IL-6, participating in the pathogenesis of both psoriasis and non-alcoholic fatty liver disease (NFLD)." (PMID 41226807, 2025). "Psoriasis, as an inflammatory, immune disease, significantly elevates the levels of inflammatory factors and cytokines, such as TNF-α and IL-6." (PMID 41465997, 2025). "As we can see, additional preconditioning of hUCB-MSCs with proinflammatory cytokines (IL-17, IL-22, and TNF-α), which are elevated in patients with psoriasis, promotes higher expression of IL-6 protein." (PMID 40906403, 2025). "We thus blocked the proinflammatory cytokines TNF-α, IL-6, IL-1β, and IL-23A, which are known to be crucial to γδ T cell activation, in WT and Acvr1b-Lyz2cre mice during psoriasis." (PMID 40067393, 2025). "miR-21 also inhibits TIMP-3 expression, resulting in the increased release of TNF-α, exacerbating the immune response in psoriasis." (PMID 39997616, 2025). "For example, in patients with psoriasis, more thorough inhibition of inflammation can be achieved by simultaneously targeting TNF-α and IL-17, which is difficult to accomplish in traditional antibody therapy." (PMID 40909165, 2025). "Biological treatments like anti-TNFα and anti-IL-23 antibodies have revolutionized psoriasis management by targeting key cytokines." (PMID 40943056, 2025). "This substantial difference was found to be highly statistically significant (p < 0.001), underscoring TNF-α and IL-6′s role as key pro-inflammatory cytokines in the pathogenesis of psoriasis." (PMID 40733073, 2025). "TNF-α is produced by various cell types involved in psoriasis progression, including keratinocytes, dendritic cells (DCs), neutrophils, mast cells, natural killer T (NKT) cells, and T-helper cells (Th1, Th17, Th22)." (PMID 40343299, 2025). "To further explore the inflammatory cytokines regulated by TP treatment, we extracted serum from the mice and analyzed the expression of inflammatory genes, such as IL-17A, IL-22, IL-23, TNF-α, and IL-6, which were closely related to psoriasis pathogenesis." (PMID 40365308, 2025). "Molecules targeting TNF-a, IL-23 and IL-17 have demonstrated significant efficacy, which highlights the essential role of TNF-a and the IL-23/IL-17 axis in psoriasis development." (PMID 40003621, 2025). "We conducted an additional sensitivity analysis including patients with psoriasis who received methotrexate or TNF inhibitors." (PMID 40995368, 2025). "TNF-α, IL-17 and IL-23, are the key cytokines driving psoriasis, contributing to epidermal hyperproliferation and inappropriate keratinocytes differentiation, vascular angiogenesis and inflammatory cell infiltration." (PMID 40584532, 2025).
psoriasis (continued). "Systematic reviews of real-world cases provide insights into clinical characteristics (e.g., age of onset, time to onset) and treatment responses in TNF-α inhibitor-induced psoriasis, but reliance on published cases risks reporting bias." (PMID 40948748, 2025). "On the other hand, anti-TNF drugs have been shown to have a less pronounced effect on these mental comorbidities in psoriasis, with guselkumab being superior to the TNF-antagonist adalimumab." (PMID 40077004, 2025). "Studies have demonstrated that patients with active psoriasisexhibit elevated TNF-α, IL-6 and IL-17 levels, which positively correlate with Psoriasis Area and Severity Index (PASI) scores." (PMID 41393395, 2025). "In psoriasis, TNF-α drives the inflammatory cascade, contributing to the skin lesions seen in affected individuals." (PMID 40310305, 2025). "Biological agents reduce the skin involvement in psoriasis patients through multiple mechanisms, thus explaining the correlation between TNF-α serum levels after 3 months of therapy and the improvement of the PASI scores, as demonstrated in the current study." (PMID 40699767, 2025). "These antibodies can act as antagonists of TNF-α and IL-12/23 p40 and have a blocking effect on the formation of psoriasis in mice." (PMID 40909165, 2025). "Chronic systemic inflammation in psoriasis is mediated by cytokines such as tumor necrosis factor (TNF), interleukin (IL-17, and IL-23), which are also involved in atherosclerosis and other cardiovascular diseases." (PMID 40303403, 2025). "Drug survival of biologics for psoriasis has reported to be lower in females than males for first-generation biologics (TNF-α/interleukin (IL) 12/23 inhibitors (i)); insights for newer biologics (IL17i and IL23i) are scarce." (PMID 40183107, 2025). "In psoriasis, TNF-α and inducible nitric oxide synthase (iNOS)-producing DCs (Tip-DCs) and 6-sulfoLacNAc DCs (slan-DCs) have been described as iDCs." (PMID 40427630, 2025). "Biological agents, including TNF inhibitors, IL-17 inhibitors, and IL-12/23 inhibitors, have demonstrated significant efficacy in the treatment of psoriasis." (PMID 41560729, 2025). "In recent years, with increasing understanding of psoriasis pathogenesis, biological agents that target interleukin (IL)-17, IL-23, and tumor necrosis factor-alpha have been widely applied for the treatment of psoriasis." (PMID 41567644, 2025). "CBD has been shown to inhibit key pro-inflammatory cytokines, such as TNF-α, IL-17, and IL-23, which are central to the pathogenesis of psoriasis." (PMID 41008526, 2025). "The diet is rich in polyphenols, omega- 3 fatty acids, and fiber, which can modulate systemic inflammation by reducing pro-inflammatory cytokines such as TNF-α, IL- 6, and IL- 17—key mediators in psoriasis pathogenesis." (PMID 40358870, 2025). "Exhibiting anti-inflammatory properties, aloe vera inhibits the arachidonic acid pathway and reduces TNF-α levels, contributing to its potential in psoriasis treatment." (PMID 40690118, 2025). "In turn, TNF‐α inhibitor was found to have a beneficial effect not only for the successful management of psoriasis but also for the amelioration of periodontal outcomes." (PMID 40277096, 2025). "Positive outcomes have been observed when using Tumor Necrosis Factor Alpha (TNF-α) inhibitors and biological therapies that target selectins to control the functioning of endothelial cells and reduce inflammation in psoriasis and related conditions." (PMID 39859506, 2025). "NF-κB is a pivotal transcription factor implicated in numerous skin inflammatory conditions, including psoriasis, and is known to be highly activated by TNFα." (PMID 40430467, 2025). "In psoriasis treatment, luteolin has shown strong anti-inflammatory properties in keratinocytes by inhibiting TNF-α-induced production of inflammatory mediators, including IL-6, IL-8, and VEGF." (PMID 40161116, 2025).
psoriasis (continued). "Anti–TNF therapies (e.g. etanercept, adalimumab) are highly effective for psoriasis, and their use in our case initially helped control skin and joint symptoms." (PMID 40861474, 2025). "AD-MSCs have immunomodulatory potential in the treatment of psoriasis by inhibiting the production of Th17-related cytokines, such as IL-17A and TNF-α, which alleviates imiquimod (IMQ)-induced skin pathological changes associated with psoriasis in mice." (PMID 40427630, 2025). "Among TNF-α inhibitors, infliximab is the most effective drug for treating psoriasis, followed by adalimumab, while etanercept exhibits the weakest therapeutic effect in this indication." (PMID 41002407, 2025). "Biologics approved by the FDA for the treatment of psoriasis include inhibitors to TNF-α, such as certolizumab, adalimumab, infliximab, and etanercept." (PMID 40109802, 2025). "Studies with anti-TNF therapies in psoriasis reveal that TNF-α inhibition can impair healing, indicating the cytokine’s role in skin repair and homeostasis." (PMID 40760097, 2025). "The most dramatic acceleration occurred during 2005–2015, when research output surged from 262 to 742 annual publications, coinciding with the widespread adoption of TNF-α inhibitors for psoriasis treatment that revolutionized therapeutic approaches." (PMID 41011289, 2025). "In our case, we observed elevated IFN-α levels instead of activation of the IL-17/23 axis, indicating a unique inflammatory pathway in TNF inhibitor-induced psoriasis." (PMID 40678000, 2025). "Inflammation in psoriasis is primarily driven by T-helper (Th) 17 and Th1 cells and is mediated by cytokines such as tumor necrosis factor (TNF)-⍺, interleukin (IL)-17, and IL-23." (PMID 40109802, 2025). "Patients with moderate-to-severe psoriasis were enrolled before treatment with anti-TNFα (n = 16) or anti-IL-23 (n = 18)." (PMID 40943056, 2025). "For example, elevated levels of TNF-α and IL-17 correlate with disease severity as measured by the Psoriasis Area and Severity Index (PASI)." (PMID 40243475, 2025). "Pathogens such as Staphylococcus aureus and HCV can trigger or exacerbate psoriasis, potentially through superantigen activation of skin-homing T cells and upregulation of tumor necrosis factor." (PMID 40546556, 2025). "The development of MEDFs during biologic therapy for psoriasis, including anti-IL-23 agents (ustekinumab, n = 2), anti-TNF-α agents (etanercept and adalimumab, n = 1), and anti-CD11a therapy (efalizumab, n = 1), has been reported." (PMID 41280943, 2025). "Psoriasis and hidradenitis suppurativa are driven by chronic inflammation involving TNF-alpha and the IL-23/IL-17 axis." (PMID 40546629, 2025). "After anti-TNF treatment, Th1 and Th17 cell frequencies decrease in psoriasis patients, reinforcing the critical role of the IL-23/Th17 axis in disease pathology." (PMID 40303401, 2025). "Neutrophils play a role not only in local inflammation but also in promoting systemic immune responses by releasing pro-inflammatory cytokines such as IL-17 and TNF-α, thereby contributing to the chronic and relapsing nature of psoriasis." (PMID 41179868, 2025). "Tumor necrosis factor-alpha (TNFα) is a key driver of inflammatory responses in psoriasis, although systemic biologic therapies effectively targeting TNFα are expensive and have many adverse effects." (PMID 40724842, 2025). "In turn, hBD-2 in patients with psoriasis or RA increases the production of TNF-α, IFN-γ, IL-10, IL-1β, IL-6, and IL-22." (PMID 40062148, 2025). "Various treatments for psoriasis were used in our study group, with phototherapy being the most common (8.3%), followed by methotrexate (3.1%), anti-TNF agents (1.4%), anti-IL-12/23 agents (0.5%), JAK inhibitors (0.4%), and anti-IL-17 agents (0.3%)." (PMID 41155795, 2025).
psoriasis (continued). "The formation of initial non-calcifying atherosclerotic plaque and endothelial inflammation has been observed, with the involvement of IL-6, IL-17 and TNF-α, whose levels are elevated in psoriasis, being postulated." (PMID 40584532, 2025). "Tumor necrosis factor-alpha (TNF-A) antagonist who has shown great success in controlling both psoriasis and PsA, has been reported to precipitate existing SLE." (PMID 40557031, 2025). "Th1 cells enhance immune responses by releasing proinflammatory cytokines such as IFN-γ and TNF-α, which are crucial in psoriasis development." (PMID 40906403, 2025). "Adipose tissue has been identified not only as an active endocrine organ, but also an immune organ that produces varied immune cells and inflammatory-related cytokines such as TNF-α, leptin, and IL-6, which exacerbate the inflammatory processes in psoriasis." (PMID 40796893, 2025). "In terms of treatment patterns and efficacy, the biologic agents administered most often in our cohort were TNF inhibitors, reflecting their status among the prioritized biologic agents for the treatment of psoriasis by Clalit Health Services." (PMID 40649154, 2025). "Other than TNF-α, some authors associate PPP a disease in the spectrum of psoriasis, and recently the IL-23/IL-17 inflammatory pathway has been suggested to play an important role in immune-mediated inflammatory diseases (IMID), as well as in PPP." (PMID 40709177, 2025). "Adalimumab, a TNF-α inhibitor, secukinumab, an IL-17 inhibitor, and ustekinumab, which targets interleukin IL-12/23p40, are effective treatments for psoriasis and have shown potential in treating psoriasis concomitant with DM." (PMID 39859462, 2025). "These include infliximab, another TNF-α inhibitor; ustekinumab, an IL-12/IL-23 inhibitor commonly used in psoriasis and CD; and secukinumab, an IL-17 inhibitor." (PMID 40136593, 2025). "Taken together, these findings demonstrate that the central mechanism of psoriasis is related closely to adaptive immune pathways comprising IL-17 and IL-23, together with the pivotal roles of Th17 cells and TNF-α." (PMID 40920623, 2025). "The complementary roles of TNF-α and IL-17A in driving inflammation make them critical therapeutic targets and biomarkers in psoriasis research." (PMID 40892753, 2025). "In contrast, the drug survival of IL-17 inhibitors used for psoriasis aggravation was comparable to that of TNF inhibitors." (PMID 40615873, 2025). "Key immunological mediators, including interleukins (IL-1, IL-6, IL-17), TNF-α, TLRs, and NF-κB, play pivotal roles in the pathogenesis of psoriasis by driving pro-inflammatory cascades and activating T lymphocytes." (PMID 40558675, 2025). "Biologic agents, such as TNF inhibitors, are a mainstay in the treatment of RA and other inflammatory conditions, such as inflammatory bowel disease or psoriasis, offering significant therapeutic benefits." (PMID 41158918, 2025). "TNF-α is a key downstream effector cytokine across diverse areas of PsA, and TNF-α inhibitors have been widely used for the treatment of PsA, and they have shown efficacy in the prevention of PsA in patients with psoriasis." (PMID 40471688, 2025). "Inflammatory cytokines, mainly IL-6 and TNF-α, are involved in the inflammatory process of psoriasis." (PMID 40004904, 2025). "Another important finding of this study is a possible correlation between the upregulation of miR-205 and the downregulation of TNF-α in treated patients with psoriasis." (PMID 39044928, 2024). "We obtained statistical significance with a P value of <0.05 only for TNF-α, with significantly higher levels in the psoriasis group." (PMID 39044928, 2024). "Conversely, blocking the inflammatory factors TNF, IL-23, IL-17A, or the corresponding receptor IL-17RA has been shown to be effective in the treatment of psoriasis." (PMID 38255845, 2024).
psoriasis (continued). "Regarding the most important inflammatory cytokine, TNF-α, we were able to demonstrate a highly significant difference in TNF-α levels between the psoriasis and control groups." (PMID 39044928, 2024). "Recent progress in biological therapies for psoriasis has revealed the fundamental roles of tumour necrosis factor‐α (TNF‐α), interleukin (IL)‐23p19 and IL‐17A axis in pathogenesis." (PMID 39624730, 2024). "Psoriasis involves biomarkers such as TNF-α, IL-23, and HLA genes, shaping treatments like IL23 and IL17 inhibitors." (PMID 38666916, 2024). "One of the most important roles that miR-155 reportedly has in the pathogenesis of psoriasis is the regulation of T cells and dendritic cells, but it also modulates inflammatory cytokines such as IL-17, IL-23, and TNF-α." (PMID 39044928, 2024). "These agents, including TNF-α inhibitors, IL-17 antagonists, and IL-12/23 antagonists 12, have been demonstrated to effectively ameliorate the symptoms of psoriasis." (PMID 39479439, 2024). "Paradoxical psoriasis has occurred in approximately 5% of patients on chronic TNF antagonist treatment." (PMID 39403182, 2024). "A subset of inflammatory DCs, TIP-DCs, secrete TNF and inducible nitric oxide synthase (iNOS) with a pro-inflammatory response in patients with psoriasis." (PMID 38793117, 2024). "Etanercept works by blocking the effects of TNF-alpha, whose level is elevated in psoriasis and multiple other immune-mediated diseases, such as Crohn’s disease, ulcerative colitis, rheumatoid arthritis, psoriatic arthritis, and ankylosing spondylitis." (PMID 39201000, 2024). "As a result, societies, such as the National Psoriasis Foundation, call for yearly screening for TB in patients on TNF-⍺ therapy." (PMID 38939259, 2024). "The present study showed that, in this group of psoriasis patients, biological therapies decrease serum levels of the proinflammatory cytokines TNF-α, IL-23 and IL-17F." (PMID 39057098, 2024). "The levels of pro-inflammatory cytokines such as tumor necrosis factor-α, interleukin 1β, and interleukin 6 are elevated in psoriasis and participate in the activation of the lectin-like oxidized low-density lipoprotein receptor-1." (PMID 39085887, 2024). "The two most common are utilization of (i) a cytokine cocktail characteristic of psoriasis—IL-17A, IL-22, IL-1α, oncostatin M, and TNFα—so called M5, or (ii) imiquimod." (PMID 38672088, 2024). "The outcomes derived from numerous genome-wide association studies (GWAS) and clinical trials corroborate the pivotal involvement of TNF/IL-17/IL-23 signaling pathways in the psoriasis etiology." (PMID 39311381, 2024). "Several TNF inhibitors, such as adalimumab and etanercept, have been approved for treating moderate-to-severe psoriasis; however, all with a variable efficiency among different patients." (PMID 38303723, 2024). "Taken together, our observations identify WNT5A+/IL24+ fibroblasts as an IL-17/TNF dependent, inflammatory cell state, that in psoriasis, is rapidly normalized by IL-23 blockade." (PMID 38291032, 2024). "Effectively, Sialostatin L didn’t show any significant inhibition of IL-6, although psoriasis-related pro-inflammatory cytokines (TNF-α, IL-22, IL-23/IL-17) expression was reduced." (PMID 38444844, 2024). "During UNCOVER-2 and UNCOVER-3 trials where ixekizumab (an IL-17 inhibitor) was versus etanercept (a TNF-α inhibitor) or placebo with psoriasis, two MACEs events were reported in the ixekizumab group." (PMID 38384460, 2024). "This case illustrates the potential for Betamethasone diproprionate/calcipotriol (Enstilar) topical foam use as a treatment approach for anti-tumor necrosis factor-alpha inhibitor-induced linear psoriasis." (PMID 39665032, 2024). "In psoriasis, IL-17A is a primary inducer of both S100 proteins, especially koebnerisin, whereas other Th17-related cytokines, such as TNF-α and IL-22, differently regulate their expression in epidermal keratinocytes." (PMID 39744637, 2024).